HDAC7 (histone deacetylase 7)
Diseases named in the same sentence as HDAC7 in open-access papers (continued):
Sharing a sentence is not in itself a finding about the gene and the disease.
tumor (continued). "This also suggests that the DNMT3a-HDAC7 signaling axis may promote tumour proliferation mainly by regulating the tumour cell cycle, which also needs to be further confirmed." (PMID 39990668, 2025). "Furthermore, we examined the link between HDAC7 mRNA levels and the immune microenvironment of tumors to deepen our comprehension of HDAC7's influence on anti-tumor immunity and HCC development." (PMID 40861819, 2025). "Conversely, overexpression of HDAC7 reversed the attenuation of tumour growth and metastasis and the suppression of c-Myc and ZEB1 expression mediated by downregulation of DNMT3a, further indicating the existence of positive feedback regulation between DNMT3a and HDAC7 in LUAD." (PMID 39990668, 2025). "Only HDAC7 was positively correlated with MDM infiltration, MES-enriched score, indicating that HDAC7 is closely associated with MES transition and formation of a suppressive tumour immune microenvironment." (PMID 39629136, 2024). "Additionally, miR‐489 has been found to target HDAC7, thereby suppressing tumor growth and invasion in CRC." (PMID 38827027, 2024). "In addition, in vivo experiments revealed that HDAC7 knockdown significantly inhibited tumour growth and prolonged the survival time of tumour-bearing mice." (PMID 39629136, 2024). "Moreover, statistical analysis also suggested that HDAC7 protein expression in tumours was higher than that in normal tissues." (PMID 39431349, 2024). "This may suggest a strong positive relationship between HDAC7 and tumor infiltrating cells (TILs), especially considering CD4+ T cell populations whose levels generally correlate positively with HDAC7 expression and negatively with HDAC2 expression." (PMID 39063083, 2024). "After this, as demonstrated in, the tumour growth, volume and weight were significantly decreased in HDAC7 KO groups compared with control groups, thereby suggesting inhibition of HDAC7 could depress cancer cell growth in vivo." (PMID 39431349, 2024). "Additionally, database analysis showed that HDAC7 expression was substantially higher in distant metastatic tumor tissues than in primary CRC tissues." (PMID 38827027, 2024). "Furthermore, we determined HDAC7 expression in both the tumour tissues and normal tissues by Immunohistochemistry (IHC), and found that HDAC7 is upregulated in tumour compared with normal tissue." (PMID 39431349, 2024). "It was reported that HDAC7 promotes tumor growth and invasion in CRC." (PMID 38827027, 2024). "Conversely, GBM tumour spheroids with HDAC7 overexpression exhibited a stronger invasive capacity." (PMID 39629136, 2024). "Furthermore, we looked at the levels of chemoattractants in all tested tumor types regarding HDAC2 or HDAC7 expression and observed that HDAC7 upregulation significantly associates with elevation of chemokines and their recognizing receptors." (PMID 39063083, 2024). "Furthermore, the combination of HDAC7 knockdown and radiotherapy resulted in a significant reduction in tumour size and an extension of the survival time of tumour-bearing mice." (PMID 39629136, 2024). "In murine model, HDAC7 KO significantly decreased the tumour burden." (PMID 39431349, 2024). "Further, HDAC7 knockdown decreased in vivo tumour growth in a mouse xenograft model." (PMID 35303381, 2023). "In summary, these results suggest that HDAC71 is highly correlated with earlier tumor clinical staging and longer survival time, further suggesting that HDAC7 may be a biomarker for better prognosis in DLBCL patients." (PMID 37960766, 2023). "Similarly, HDAC7 protein levels were increased in cancer stem cells (CSCs) versus non‐stem tumour cells." (PMID 35303381, 2023). "In addition, multiple elements were analyzed for HDAC7 in DLBCL, including mutation features, nomogram, PPI, tumor immune infiltration, immune cell pathways, and checkpoint molecules." (PMID 37960766, 2023).
tumor (continued). "To further validate the proliferation-promoting role of HDAC7 in vivo, we established tumor xenograft nude mice models with LV-Control/LV-HDAC7 C918 cells and found that the weight of xenograft tumors in the HDAC7 overexpression group was evidently greater (P < 0.05)." (PMID 36653340, 2023). "A recent study reported that HDAC7/β-catenin/c-Myc could form a positive feedback loop to enhance tumor cell growth in ESCC." (PMID 36653340, 2023). "Studies reveal that the carcinogenic effect of HDAC7 depends on the amplification of c-Myc, which promotes tumor cell escape from the cellular senescence process and facilitates tumor cell growth by suppressing the expression of p21/p27, thereby accelerating the G1-S cell cycle transition." (PMID 36653340, 2023). "Recent researches revealed that oncogenic actions of HDAC7 are dependent on the c-Myc amplification, since c-Myc helps tumor cells escape from cellular senescence process and promotes tumor cell growth via inhibiting p21/p27 expression thus accelerating G1–S cell cycle transition." (PMID 36163081, 2022). "Thus, the levels of HDAC1 and HDAC7 are correlated with tumor characteristics, such as grade and stage." (PMID 34360879, 2021). "Correctively, miR-489 played as a tumor suppressor in GC cell growth by targeting HDAC7, and miR-489 might function as a novel biomarker for diagnosis or therapeutic targets of human GC." (PMID 32284070, 2020). "Moreover, selective HDAC1 and HDAC7 inhibitors preferentially target CSCs and inhibit xenograft tumor growth in OC." (PMID 31277278, 2019). "To test our hypothesis, we investigated if expression of Stat3Y705F, a dnStat3, could rescue lung tumor-suppression role of Hdac7 mutant in mice." (PMID 29126425, 2017). "Our data showing a decreased beta cell number due to increased apoptosis with Hdac7 overexpression are also supported by a previous study in cancer cells, which demonstrated that ectopic expression of HDAC7 promotes apoptosis and inhibits tumour growth." (PMID 27796421, 2017). "Interestingly, LPA/PKD-1 signaling suppresses CD36 transcription and reprograms MVECs for arteriogenic gene expression via a nuclear HDAC7-FoxO1 complex, implicating microvascular remodeling and tumor arteriogenesis." (PMID 27200349, 2016). "Moreover, the estimated ratio of HDAC7 synthesis in Panc-1 tumor cells transformed with the control vector (pCDNA3) versus those that overexpress HDAC7 was approximately 1 to 300%." (PMID 25275504, 2014). "Hence, our findings provide compelling evidence that HDAC7 or its metabolic sequelae could be targeted to block tumor progression in one of the most common malignancies." (PMID 40465706, 2025). "Therefore, HDAC7 could potentially function as a potent predictor for tumor prognosis and a promising target for mitigating drug resistance in tumors." (PMID 38487728, 2024). "Importantly, HDAC7 promoted tumour cell proliferation and invasion in both CRC cell lines and mice, implying that it may have a functional role in CRC progression." (PMID 35303381, 2023). "Moreover, FGF18 silencing could dramatically attenuate subcutaneous tumor growth in the Calu-1 HDAC7 overexpression group." (PMID 35277183, 2022). "HDAC7 overexpression promoted malignancy and reduced TKI sensitivity, whereas HDAC7 knockdown or TSA treatment suppressed tumour growth and enhanced TKI sensitivity in vivo." (PMID 42094614, 2026). "Taken together, we identify HDAC7 as a central regulator of cellular exhaustion and apoptosis of peripheral CD8+ T cells, controlling CD8+ T cell dependent anti-tumor and anti-viral immunity in mice." (PMID 42206036, 2026). "The immunoregulatory function of HDAC7 was evaluated using CD8 + T cell co-culture assays and tumor models in humanized NOG (HuNOG) mice." (PMID 41444923, 2025). "There isn’t known selective inhibitor of HDAC7, but the selective class IIa HDAC inhibitor (TMP195) has been well-characterized to inhibit HDAC7, with reported anti-tumor activities in preclinical studies." (PMID 39806423, 2025).
tumor (continued). "We found that HDAC family member HDAC7 was up-regulated by TRIM28-mediated SUMOylation in MES GBM and created a pro-tumour microenvironment by promoting MES transition of GSC and MDM-mediated immunosuppressive transformation." (PMID 39629136, 2024). "Integrins play a key role in tumour invasion, matrix remodelling and MAPK signalling pathways 31, 32, which were significantly enriched by HDAC7-upregulated genes." (PMID 39629136, 2024). "The clinical relevance of our experimental findings was supported by immunohistochemical staining analyses demonstrating that the expression of HDAC7, ITGB1, LGALS3 and CD44 was highest in GBM tumours and was negatively correlated with SOX8 expression." (PMID 39629136, 2024). "In our comprehensive analysis of HDACs in DLBCL patients using public databases, we found that the expression levels of HDAC1, HDAC2, HDAC3, HDAC6, HDAC7, HDAC8, and HDAC9 were higher in tumor tissues compared to normal control for the first time." (PMID 38168914, 2024). "In the terms of mechanism, inhibition of HDAC7 induces remarkably decrease at the levels of p‐AKT and p‐mTOR, which is extremely important for tumour progression, resulting in arresting of cell proliferation and invasion." (PMID 39431349, 2024). "Analysis of the transcriptomic data revealed that LGALS3 (an important regulator of the tumour microenvironment 28-30), which is a target gene of the transcription factor JUN, was the most significantly decreased gene following HDAC7 knockdown." (PMID 39629136, 2024). "In other words, HDAC7-high and HDAC2-low patients have significantly higher tumor immune and stromal infiltration levels in many tumors." (PMID 39063083, 2024). "Thus, HDAC7 may promote tumour growth via sustaining angiogenesis." (PMID 35303381, 2023). "Reduced miR‐489 led to derepression of HDAC7 expression and subsequent activation of the PI3K/AKT pathway, a signalling pathway with a well‐known role in tumour development." (PMID 35303381, 2023). "Using the Wilcoxon rank sum test, we used the SCNA module to explore the correlation between the level of tumor immune infiltration in DLBCL and different somatic copy number changes in HDAC7." (PMID 37960766, 2023). "The elevated expression of HDAC7 or FGF18 was positively correlated with poor prognosis, tumor–node–metastasis (TNM) stage, and tumor differentiation of NSCLC patients." (PMID 35277183, 2022). "Studies have shown that genome-wide histone acetylation levels are generally reduced in tumor cells, among which HDAC1, HDAC5 and HDAC7 are regarded as tumor markers." (PMID 35545840, 2022). "HDAC1 (p = 0.05), HDAC3 (p = 0.02), the second probe of HDAC5 (p = 0.04) and of HDAC7 (p = 0.03), and HDAC8 (p = 0.004), were increased in tumours with 8q gain, while HDAC11 was decreased (p = 0.002)." (PMID 33316946, 2020). "Mean mRNA transcription levels of PA for HDAC7 and HDAC2 were higher when compared to their counterpart biopsies taken at the tumor periphery (p = 0.0346, 0.0053, respectively)." (PMID 25275504, 2014). "Our work identifies HDAC7 as a molecular mediator that governs ATF3's functional plasticity through competitive cofactor recruitment, positioning HDAC7 inhibition as a therapeutic strategy to reactivate ATF3-mediated tumor suppression in CRC." (PMID 42157949, 2026). "In addition, upregulated expression of HDAC7 was positively correlated with high T stage, lymphatic invasion, high TNM stage, and poor tumour differentiation." (PMID 39990668, 2025). "Although the data presented support a role for HDAC7’s effects on BCAA catabolism, they do not exclude alternate effects of HDAC7 on the expression of genes that affect tumor progression." (PMID 40465706, 2025). "Furthermore, the expression of HDAC7 and MES markers was progressively upregulated with tumour progression, as demonstrated by Monocle2 pseudotime analysis." (PMID 39629136, 2024).
tumor (continued). "To validate the observation of HDAC-dependent tumor microenvironment, we employed the ESTIMATE tool and observed that the purity, immune, and stromal scores correlate highly positively with HDAC7 gene expression in selected solid tumors, except for OV and BLCA." (PMID 39063083, 2024). "To investigate whether TTYH3 or HDAC7 participate in CRC angiogenesis, we established mice subcutaneous tumor models." (PMID 38827027, 2024). "Further, another study of resected patient CRC tissues reported that the microRNA, miR‐489, which represses HDAC7 expression, was significantly downregulated in tumour tissues by comparison to adjacent noncancerous tissues." (PMID 35303381, 2023). "However, there is quite a consensus in the literature that HDAC4, HDAC7, HDAC9, SIRT2, and SIRT7 are upregulated in GC and seem to be pro-tumor factors, whereas SIRT4, SIRT5, and SIRT6, which are downregulated, seem to have a tumor suppressor function." (PMID 36358890, 2022). "In order to investigate whether USP10 and HDAC7 signaling is specific for NSCLC tissues, we further analyzed the USP10 and HDAC7 co-expression by IHC staining in 71 paired tumor–normal tissue samples." (PMID 35277183, 2022). "Moreover, as an independent prognostic factor for NSCLC patients, high HDAC7 was positively correlated with TNM stage and tumor differentiation." (PMID 35277183, 2022). "In summary, our data reveal that HDAC7 functions as an oncogene in NPC, and promotes the oncogenicity of NPC cells by inhibiting miR-4465 expression, and subsequently upregulating EphA2, and miR-4465 functions as a tumor suppressor in NPC." (PMID 32376822, 2020). "With regard to both HDAC5 as well as HDAC7 expression, we found significant differences between D3 vs. M3 tumours for only one of the two probes that had been used (HDAC5 probe 1 p = 0.90, HDAC5 probe 2 p = 0.004, HDAC7 probe 1 p = 0.30, HDAC7 probe 2 p = 0.02)." (PMID 33316946, 2020). "Moreover, overexpression of HDAC7 did not significantly modify the growth capacity of parental cells over the time period of culture (p = 0.3161) suggesting therefore that additional copies of HDAC7 encoding gene are not necessary to reach optimal growth for the parental tumor Panc-1 cells." (PMID 25275504, 2014). "Research has shown that the absence of HDAC7 inhibits cell cycle development and reactivates cell aging in a c-Myc-dependent manner, inhibiting the proliferation of human cancer cells, indicating that HDAC7 plays an important role in tumor proliferation." (PMID 40901472, 2025). "Importantly, the TGF-β/HDAC7 signaling pathway can repress oxidative phosphorylation in RCC, and the administration of TGF-β inhibitor restores the expression of TCA cycle enzymes and inhibits tumor progression in the orthotopic RCC model." (PMID 35456435, 2022). "Furthermore, the NSCLC patients with deep tumor invasion and/or larger tumors (T3/T4), high American Joint Committee on Cancer (AJCC) 8th stage (stage III–IV) and lymph node metastasis (N1–N3) had higher HDAC7 expression." (PMID 35277183, 2022). "Not surprisingly, since HDAC7 is regulated at multiple levels, including protein stability and nuclear–cytoplasmic shuttling, we have not found a correlation between its mRNA levels and luminal A tumour aggressiveness." (PMID 31081251, 2019). "HDAC7 expression was upregulated in 15 samples (~45.5%) and down-regulated in 10 samples compared to that in tumor-adjacent tissues, while no HDAC7 protein could be detected in both lung tumors and tumor-adjacent tissue from 8 patients (~24.2%)." (PMID 29126425, 2017). "However, no study has been conducted yet to investigate whether HDAC7 regulate the classic AKT/mTOR pathway, which plays an indispensable role in the progression of tumour." (PMID 39431349, 2024).
cancer (47 papers, 2006 to 2026). A tumor composed of atypical neoplastic, often pleomorphic cells that invade other tissues. "As an important member of the HDAC family, HDAC7 has been found in earlier investigations to be associated with various inflammatory diseases and cancers." (PMID 40861819, 2025). "Aberrant HDACs expressions, especially HDAC7 is implicated in the onset and progression of many cancers." (PMID 39431349, 2024). "Considering the immune cell pathways, we propose an association between the expression of HDAC7 mRNA and 28 types of TILs in human cancer." (PMID 37960766, 2023). "This review focuses on the cell biology of HDAC7, including the regulation of its cellular localisation and molecular mechanisms of action, as well as its associative and causal links with cancer and inflammatory, metabolic and fibrotic diseases." (PMID 35303381, 2023). "Aberrant expression and/or function of HDAC7 has been linked to cancer, including colorectal, gastric, pancreatic and brain cancer." (PMID 35303381, 2023). "One of the important FDA-approved drug targets, HDAC7 also could offer novel therapeutic application to explore the underlying mechanism of cancer progression and perturbation of its ligands systems for development of better or optimized drug candidates." (PMID 36354673, 2022). "Class IIa histone deacetylase 7 (HDAC7) regulates transcription primarily through scaffolding functions, but its molecular mechanisms in cancer pathogenesis remain incompletely understood." (PMID 42157949, 2026). "The investigation examined HDAC7 gene expression signatures across various human cancers and healthy tissues using TCGA-derived information." (PMID 40861819, 2025). "In this study, we demonstrated that LukS-PV targeting C5aR1 inhibits HCC cell proliferation by the HDAC7-Wnt/β-catenin axis, suggesting the strong potential of LukS-PV as a therapeutic cancer drug for HCC treatment." (PMID 39736396, 2025). "This indicates that HDAC7 plays diverse and crucial roles in cancer development and related BPs through these pathways and molecular mechanisms." (PMID 40861819, 2025). "In contrast, HDAC7 expression level positively correlates with increased immune cells’ abundance, suggesting an augmented cancer immunogenicity." (PMID 39063083, 2024). "Histone deacetylase 7 (HDAC7) is very important in regulating cancer progression, but the significance and effect of HDAC7 on CM progression are unclear." (PMID 36653340, 2023). "Overexpressing HDAC7 in the cancer cell lines HK1 and 5–8F enhanced cell proliferation, migration and invasion." (PMID 35303381, 2023). "Tip60 interacts with STAT3 and serves as a co-repressor for STAT3 in cancer cells via recruitment of HDAC7 to STAT3 target genes." (PMID 36768434, 2023). "To date, HDAC7 inhibitors have mainly been studied in cancer, with emerging reports on regulatory effects in the central nervous system and neurodegenerative conditions, and potential roles in inflammatory conditions and metabolic dysfunction." (PMID 35303381, 2023). "RNA sequencing data and clinical information for HDAC7 in DLBCL were collected from the cancer genome atlas database and analyzed using R software." (PMID 37960766, 2023). "Previous research has reported that HDAC7 plays an indispensable pro-proliferative role in some cancer cells, including MCF-7, HeLa, and HCT116." (PMID 36653340, 2023). "Previous studies have found that HDAC7 is a crucial pro-proliferative factor of cancer cells, such as Hela, HCT116, and MCF-7." (PMID 35277183, 2022). "Previous studies revealed that ectopic HDAC7 expression enhanced cancer cell proliferation, angiogenesis and metastasis." (PMID 36163081, 2022). "A closer look at these factors identified a group of three histone deacetylases (Hdac4, Hdac7, Hdac8) with reported implications in cancer patient's prognosis and with a wide range of available specific inhibitory compounds." (PMID 35016723, 2022).